MTOR (mechanistic target of rapamycin kinase)
Diseases named in the same sentence as MTOR in open-access papers (continued):
Sharing a sentence is not in itself a finding about the gene and the disease.
idiopathic pulmonary fibrosis (24 papers, 2014 to 2025). Idiopathic pulmonary fibrosis (IPF) is a nonneoplastic pulmonary disease that is characterized by the formation of scar tissue within the lungs in the absence of any known cause. "However, PI3K and mTOR are involved in the pathogenesis of idiopathic pulmonary fibrosis (IPF)." (PMID 37489050, 2023).
memory impairment (24 papers, 2014 to 2025). "However, much further work would be required to elucidate the exact association between learning/memory impairments in AD and mTOR signaling pathway." (PMID 37721413, 2024). "Inhibition of mTOR protein expression may aid in delaying cognitive deterioration, as hyperactivation of this protein has been associated with memory impairment." (PMID 36313018, 2022). "In a study with Tg2576 mice, reducing mTOR signaling and gene expression in the hippocampus increased autophagy and decreased Aβ accumulation, protecting against memory impairments." (PMID 40842769, 2025). "More work, however, is needed to untangle the complexity of the mTOR signaling pathway to understand the effect of alcohol during fetal growth on learning and memory impairment and sensitivity to alcohol abuse, as well as alcohol relapse in adulthood." (PMID 33924998, 2021). "In fact, it is well recognized that mTOR signaling is associated with T2DM and AD pathology in several ways, suggesting its potential role in energy imbalance, learning and memory impairment, and Aβ deposition." (PMID 32372981, 2020). "In summary, our data show that a single generalized seizure and the associated memory impairments are linked, in part, to dysregulated signaling of PI3K/Akt/mTOR cascade and altered spine morphology and that these changes are transient." (PMID 28612047, 2017). "Inhibiting mTOR signaling with rapamycin not only protects against Aβ and tau pathology but also may prevent memory impairments." (PMID 37721413, 2024). "mTOR upregulation has been associated with long-term memory retrieval, as the mTORC1 inhibitor rapamycin leads to long-term, but not short-term, memory impairment." (PMID 37927260, 2023). "In Tg2576 mice, mTOR knockdown reduced amyloid deposits and ameliorated memory impairment." (PMID 33322202, 2020). "Furthermore, dual inhibition of PI3K and mTOR with BEZ reduces memory impairment induced by intrahippocampal injection of Aβ, which is associated with reduced neurodegeneration and reduced microglial activation." (PMID 31798451, 2019). "Notably, Ketamine, which is thought to exert antidepressant action through modulation of mTOR pathway activity, potentiates persistent learning and memory impairment through the PKCG-ERK signaling pathway." (PMID 28775826, 2017). "The mTOR inhibition triggers autophagy to decrease Aβ and improve T2DM and AD memory impairment." (PMID 32372981, 2020). "First, we demonstrated that LY294002, a compound known to inhibit PI3K and mTOR, as well as rapamycin, which inhibits mTOR, did not avoid memory impairment in this context." (PMID 27142962, 2016). "Silibinin leads to decreased inflammation arising from dementia and non-dementia diseases, stress, memory impairments, and oxidative damage via inhibition of NF-κB signaling pathway and affecting Akt/mTOR signaling pathway and improves cognition functions (Hwang and Kim, 2011 ▶)." (PMID 38106632, 2023). "Similarly, acupuncture at the corresponding acupoints can inhibit GSK3β/mTOR in d-galactose-treated rats and the AMPK/eEF2K/eEF2 and RhoA/ROCK signaling pathways in SAMP8 mice to promote synaptic plasticity, thereby improving memory impairment." (PMID 36211826, 2022). "Furthermore, Torin-2—a non-selective mTORC1/C2 inhibitor—and FK-506—a substance that impacts oxidative stress in a mTOR-independent manner—did not prevent fear learning and memory impairments, although the results were partially lowered by these compounds." (PMID 34209274, 2021).
status epilepticus (24 papers, 2012 to 2025). Status epilepticus is defined as a continuous seizure lasting more than 30 min, or two or more seizures without full recovery of consciousness between any of them. "The principal aims of the present study were to establish mTOR activity patterns in different cell types and brain regions following KA-induced status epilepticus and investigate the effects of chronic, systemic rapamycin treatment on susceptibility to status epilepticus." (PMID 23724051, 2013). "The association between mutations in mTOR pathway genes and epileptic network has reported, and studies in rodent models of status epilepticus demonstrate that mTOR signaling is activated by status epilepticus." (PMID 33407677, 2021). "Acute seizures activate the mTOR pathway transiently, whereas status epilepticus leads to chronic mTOR elevation." (PMID 28367137, 2017). "A previous study indicated that KA-induced status epilepticus results in substantial changes in the transcriptome and increases mTOR activity in adult animals." (PMID 26993296, 2017). "Another consideration would be to correlate seizure activity during the initiation of status epilepticus to changes in mTOR activation." (PMID 27819284, 2016). "The present study aimed to investigate the effect of the pioglitazone PPAR-γ agonist on the mTOR pathway in pentylenetetrazol (PTZ)-induced status epilepticus (SE), and examine the expression levels of the IL-1β and IL-6 inflammatory factors." (PMID 25891824, 2015). "The present study investigated the effect of the PPAR-γ agonist, pioglitazone, on the mammalian target of rapamycin (mTOR) signaling pathway in a rat model of pentylenetetrazol (PTZ)-induced status epilepticus (SE)." (PMID 25891824, 2015). "In several animal models of epileptogenesis (e.g., kainic acid [KA]- or pilocarpine-induced status epilepticus), increased mTOR activity was biochemically proven." (PMID 23724051, 2013). "Specifically, after kainic acid-induced status epilepticus, increases in mTOR activity (reflected in phosphorylation of S6) are noted 1–6 h after seizure onset, then decrease to baseline values, only to increase again 3 days after onset." (PMID 22984623, 2012). "Interestingly, a decrease of mTOR in astrocytes inhibited glutamate release within the spinal cord, which is consistent with the previously reported role of mTOR in regulating glutamate metabolism after the onset of status epilepticus." (PMID 39893345, 2025). "Regarding other immunossupressive mTOR inhibitors, it was found that repeated administration of everolimus did not prevent or ameliorate spontaneous recurrent seizures after kainic acid-induced status epilepticus in rats." (PMID 36769250, 2023). "Whether mTOR stabilizes transcripts that are induced by status epilepticus remains to be investigated." (PMID 26993296, 2017). "With regard to the second aim, we showed that chronic systemic rapamycin treatment, which inhibited mTOR signaling in hippocampi and cortex gradually led to facilitation of KA-induced status epilepticus and epileptic discharges as well as induced gross morphological changes in the brain." (PMID 23724051, 2013). "mTOR signalling is elevated following seizure in rodent models and, moreover, rapamycin has potential anticonvulsive properties in the WAG/Rij rat absence seizure model and in kianic acid-induced status epilepticus in rat." (PMID 26863447, 2016). "Administration of mTOR inhibitors, i.e. rapamycin, prevents the development of absence seizure in WAG/Rij rats, kindling seizure in Tsc1GFAPCKO mice and kainite-induced status epilepticus in rats." (PMID 25681415, 2015). "Our analysis of P-mTOR did not provide the ultimate answer if mTOR activity is indeed changed after KA-induced status epilepticus." (PMID 23724051, 2013).
dementia (23 papers, 2014 to 2025). Loss of intellectual abilities interfering with an individual's social and occupational functions. "Prior research has suggested that TSC1/2 mutations, excessive mTOR signaling, and dementias may be linked mechanistically." (PMID 35241183, 2022). "In particular, in dementia a marked up-regulation of mTOR, which relates with disease severity, has been described in humans." (PMID 29311919, 2017). "The ability to suppress mTOR in this cell line is remarkable due to an aberrant baseline mTOR overexpression just like in dementia." (PMID 29311919, 2017). "As previously noted, this may be attributed to the inhibitory activity of J147 on ATP5A, the latter of which activates the AMPK/mTOR pathway that plays a key role in aging and dementia." (PMID 37674139, 2023). "The elevated Ca2+ leads to the activation of calcium/calmodulin-dependent protein kinase kinase β (CAMKK2), which then activates the AMPK/mTOR pathway, a canonical aging- and dementia-related signaling pathway that is known to attenuate age-associated decline and extend lifespan." (PMID 37674139, 2023). "If increased mTOR activity limits the effective dose of lithium, this raises the question of whether an mTOR inhibitor such as rapamycin combined with lithium would have beneficial synergistic effects in dementia or cognitive aging." (PMID 30425653, 2018). "The novel circadian clock gene pathways that involve autophagy, mTOR, and (SIRT1) and include FoxOs and EPO offer exciting prospects for the development of new strategies to understand cognitive loss and to overcome challenges that can limit the onset and progression of dementia." (PMID 34356626, 2021). "By reducing mTOR activity and directly activating ULK1, AMPK also leads to the formation of autophagosomes and the degradation of Tau and APP, thus achieving the purpose of treating dementia." (PMID 37189611, 2023). "The reduction in biological annotation with MTOR signaling and reactive oxygen species pathways were much more pronounced for the amyloid β plaque measure, and not observed with AD diagnoses or clinical dementia." (PMID 38343831, 2024).
gallbladder cancer (23 papers, 2015 to 2025). "One study found that TOP2A promotes the proliferation and migration of gallbladder cancer cells through the PI3K/Akt/mTOR pathway, suggesting that TOP2A is associated with the poor prognosis of patients." (PMID 36004205, 2022). "Unsatisfactory results derived from the use of MET inhibitors such as cabozantinib (abnormal MET activation has been found in 12%–58% of iCCAs) PI3K/AKT/mTOR inhibitors showed exiguous responses despite 12.5% of gallbladder cancers displaying activated mutations of PIK3CA." (PMID 32423017, 2020). "FOXK1 activates the AKT/mTOR signaling pathway and promotes hyperplasia and metastasis of gallbladder cancer." (PMID 39981141, 2025). "Mutations in TUBB3 were previously reported in facial palsy and peripheral neuropathy and also reported in the development of gallbladder cancers through Akt/mTOR signal pathway." (PMID 37466845, 2023). "mTOR phosphorylation was observed in 64.1% of tumor tissues obtained from gallbladder cancer (GBC) patients, and mTOR phosphorylation levels were associated with poor prognosis in these patients." (PMID 31929797, 2019). "A number of studies have shown that the Akt/mTOR signaling pathway is over-activated in gallbladder carcinoma and deregulation of PI3K/Akt signaling is sufficient to transform gallbladder epithelial cells to cancer cells." (PMID 28212545, 2017). "Our previous studies also revealed that inhibition of mTOR suppresses human gallbladder carcinoma cell proliferation and enhances the cytotoxicity of 5-fluorouracil (5-FU) by regulating MDR1 expression." (PMID 28422725, 2017). "PTEN is a tumor suppressor gene that regulates the PTEN/PI3k/AKT/mTOR pathway, which is frequently altered in human cancers including gallbladder cancer (GBC)." (PMID 26294099, 2015). "Our findings provide a mechanistic rationale for the development of HDACIs as a single therapy, or in combination with mTOR inhibitors, in the treatment of gallbladder carcinoma." (PMID 26287365, 2015). "In the current study, it was found, for the first time, that HDACIs inhibited the proliferation and induced apoptosis of gallbladder carcinoma cells in vitro by suppressing AKT/mTOR signaling." (PMID 26287365, 2015). "Taken together, we have for the first time demonstrated that HDACIs inhibit the viability of gallbladder carcinoma cells in a dose- and time-dependent manner and cause G1 phase arrest of the cell cycle by suppressing AKT/mTOR signaling." (PMID 26287365, 2015). "Our results demonstrate that histone deacetylase inhibitors (HDACIs) suppress the proliferation of gallbladder carcinoma cell via inhibition of AKT/mTOR signaling." (PMID 26287365, 2015). "Our previous study demonstrated that an mTOR inhibitor could increase the sensitivity of gallbladder carcinoma cells to 5-FU by downregulating expression of MDR1." (PMID 28422725, 2017). "Here, we show that the histone deacetylase inhibitors (HDACIs) trichostatin-A (TSA) and suberoylanilide hydroxamic acid (SAHA) reduce the proliferation and induce apoptosis of gallbladder carcinoma cells by suppressing the AKT/mammalian target of rapamycin (mTOR) signaling." (PMID 26287365, 2015). "Furthermore, the current study revealed that HDACIs are able to inhibit AKT/mTOR signaling and its downstream targets, and that the mTOR inhibitor rapamycin reduces the viability of gallbladder carcinoma cells." (PMID 26287365, 2015). "Previously published data from our group shows that phospho-mTOR and phospho-P70S6K expression are significantly higher in human gallbladder carcinoma than in non-neoplastic tissues and that high expression of phospho-mTOR is associated with poor survival in patients with advanced GBC." (PMID 26397134, 2015). "Our findings demonstrate that ESRRG knockdown in gallbladder cancer cells significantly impairs cell proliferation and migration, accompanied by a decrease in key elements of the EMT, MAPK, and mTOR signaling pathways." (PMID 40356747, 2025).
gallbladder cancer (continued). "PABPC1 was able to stabilize lncRNA‐PAGBC in gallbladder cancer, and activates the AKT/mTOR pathway to promote tumour growth and metastasis." (PMID 38683130, 2024). "Similar results were observed in gallbladder cancer cells, where melatonin suppresses the PI3K/Akt/mTOR signaling pathway in a time-dependent manner by inhibiting the phosphorylation of PI3K, Akt and mTOR." (PMID 38473317, 2024). "Gallbladder cancer cells treated with TAM indeed induced AMPK activation, which was accompanied by decreased phosphorylation of mTOR (p‐mTOR), a critical regulator of cancer cell glycolysis, indicating impaired glycolysis." (PMID 31782270, 2020). "In gallbladder cancer, SNORA74B knockdown suppressed activation of the AKT/mechanistic target of rapamycin (mTOR) pathway via inducing PHLPP expression." (PMID 31338327, 2019). "In gallbladder cancer, TOP2A promotes cell proliferation and metastasis through the activation of the PI3K/Akt/mTOR signaling pathway, suggesting that it could serve as a therapeutic target." (PMID 40831931, 2025). "Through immunohistochemical assays, we have found that phospho-mTOR and phospho-P70S6K expression are significantly elevated in human gallbladder carcinoma compared to non-neoplastic tissues." (PMID 26397134, 2015).
hamartoma (23 papers, 2006 to 2025). A benign and excessive tumor-like growth of mature cells and normal tissues which grow in a disorganized pattern. "These mutations dysregulate the mammalian target of rapamycin (mTOR) signaling cascade, leading to abnormal cell proliferation and the formation of hamartomas with multisystem involvement." (PMID 39229295, 2024). "Hamartomas are mainly benign tumors caused by mutations in several tumor-suppressor genes and can provide a fine example of mTOR deregulation." (PMID 34449596, 2021). "So the mTOR signaling pathway was over activated, which caused their hamartoma and neuropsychiatric disorders." (PMID 32735081, 2020). "Through understanding the critical role of activation of the mTOR pathway in the tumorigenesis of TSC-associated hamartomas, therapeutic modalities of the hamartomas are changing." (PMID 24558502, 2014). "The prevalence of this genetic disorder is 1 in 6000 new-borns, where the genetic aberrant induces hyperactivity of the mammalian target of Rapamycin (mTOR) and subsequently causes a spur of multiple hamartomas in organs such as the brain, kidneys, skin, lungs, eyes and heart." (PMID 32972027, 2020). "Importantly, mutations in upstream negative regulators of mTOR cause hamartomas, haemangiomas, and cancers that are sensitive to rapamycin treatment." (PMID 16404421, 2006). "Recently, mTOR inhibitors (mTORis) have shown promise in managing symptomatic or problematic hamartomas." (PMID 40141713, 2025). "Mutations in the TSC1 and TSC2 genes result in the constitutive hyperactivation of the mammalian target of the rapamycin (mTOR) pathway, contributing to the growth of benign tumors or hamartomas in various organs." (PMID 39852149, 2025). "While mTOR inhibitors are clinically important to reduce hamartoma size, their volume tends to increase after the treatment is stopped." (PMID 38622693, 2024). "Due to dysregulated activity of the mammalian target of rapamycin (mTOR) pathway, hamartomas or benign tumors frequently occur in many organs and are often treated with mTOR inhibitors." (PMID 38455392, 2024). "The activation of the mTOR pathway due to genetic alterations of the tuberous sclerosis complex in the TSC1 or TSC2 genes in hamartomas has also been reported as well as the subsequent therapeutic implications." (PMID 38622693, 2024). "In conclusion, hamartomas were characterized by elevated mTOR pathway activity, stem-like cells, and aberrant neurogenesis within the striatum." (PMID 38107199, 2023). "Disruption of the tuberin–hamartin complex leads to overactivation of mTOR signaling and uncontrolled cell growth, resulting in hamartoma formation." (PMID 38137462, 2023). "This drug successfully helped TSC patients by inhibiting the mTOR pathway, thus preventing the growth of the life-threatening hamartomas." (PMID 32972027, 2020). "For unruptured hamartomas > 4 cm, minimally invasive procedures, including arterial embolization, radiofrequency ablation, cryoablation and partial or total nephrectomy, and other novel therapies, such as mTOR inhibitors, are recommended." (PMID 38622693, 2024). "Hamartin–Tuberin complex, a TSC1 and TSC2 gene product, is involved in cell proliferation through mTOR inhibition, with resulting hamartoma formation in the skin, nervous system, kidney, lung, bone, and elsewhere, together with abnormalities in the TSC1 and TSC2 genes." (PMID 36362756, 2022). "Preliminary data showed that mTOR inhibitors effectively control the growth of hamartomas." (PMID 24558502, 2014). "An open-label drug trial has been started with the mTOR inhibitor sirolimus (alternative name for rapamycin) to treat PHTS patients, and this drug has shown some efficacy in inhibiting the growth of lipomas, which are a type of hamartoma." (PMID 29716894, 2018).
hamartoma (continued). "A study recently reported a reduction in hamartomas in patients with PHTS after rapamycin treatment, suggesting that patients with disorders in the PTEN hamartoma tumor syndrome spectrum might respond to therapies designed to inhibit the PI3-K/mTOR pathway." (PMID 37692099, 2023). "Finally, we used this newly developed model to test whether rapamycin, an mTOR inhibitor that is currently the only PHTS therapy, can block hamartoma growth." (PMID 29716894, 2018).